SEMA4A (semaphorin 4A)
Diseases named in the same sentence as SEMA4A in open-access papers (continued):
Sharing a sentence is not in itself a finding about the gene and the disease.
Sepsis (1 paper, 2025). Sepsis is defined as life-threatening organ dysfunction caused by a dysregulated host response to infection. "We identified 307 highly expressed DEGs and 72 disease-related risk genes, culminating in the identification of three core sepsis genes including SEMA4A, LRPAP1, and NTSR1." (PMID 40756031, 2025). "By integrating multi-omics analysis and vitro experiments, we elucidate the cellular and molecular mechanisms of SEMA4A in sepsis, laying the groundwork for novel diagnostic and therapeutic approaches." (PMID 40756031, 2025). "Notably, the analysis highlighted LRPAP1, NTSR1, and SEMA4A as up-regulated risk genes in sepsis (core sepsis genes)." (PMID 40756031, 2025). "This study offers a comprehensive analysis of genes contributing to sepsis by combining transcriptomics, MR, single-cell sequencing, and in vitro experiments, with a particular emphasis on SEMA4A, LRPAP1, and NTSR1." (PMID 40756031, 2025). "Among three core sepsis genes, only SEMA4A was upregulated in the model group, whereas LRPAP1 and NTSR1 exhibited decreased expressions, contrary to previous results." (PMID 40756031, 2025). "In this study, we conducted differential gene expression and mendelian randomization (MR) analyses to target three regulated risk sepsis genes (core sepsis genes: LRPAP1, NTSR1, and SEMA4A)." (PMID 40756031, 2025). "The results confirmed significantly higher expression levels of LRPAP1, NTSR1, and SEMA4A in these additional sepsis samples compared to the control group." (PMID 40756031, 2025). "In vitro experiments using THP-1 human monocytic cells validated that SEMA4A as well as the MAPK biomarker gene ERK were up-regulated in LPS-induced sepsis cells." (PMID 40756031, 2025). "While the differential expression analysis of the dataset indicated that upregulation of NTSR1, LRPAP1, and SEMA4A in sepsis, our in vitro experiments revealed that only SEMA4A was upregulated in the model group." (PMID 40756031, 2025). "Notably, SEMA4A emerged as a potentially novel target warranting further exploration in sepsis research." (PMID 40756031, 2025). "Finally, the vitro experiments were applied to explore the most important core gene (SEMA4A) function in the sepsis." (PMID 40756031, 2025). "Subsequent differential expression and enrichment analyses revealed a significant enrichment in the MAPK signaling pathway, suggesting that SEMA4A may influence sepsis progression through the MAPK signaling pathway." (PMID 40756031, 2025). "While the specific role of SEMA4A in sepsis remains unclear." (PMID 40756031, 2025). "Our subsequent transfection experiments, silencing SEMA4A expression, further confirmed that SEMA4A can regulate the MAPK signaling pathway, positioning it as a novel upstream regulatory molecule in the pathological context of sepsis." (PMID 40756031, 2025). "Particularly, it underscores the crucial role of SEMA4A/MAPK in monocytes in the pathogenesis and progression of sepsis, offering valuable insights for potential treatment strategies." (PMID 40756031, 2025). "To gain deeper insights into the functions and pathways influenced by three core genes in sepsis, we conducted GO and KEGG enrichments among groups with high and low expression of NTSR1, LRPAP1, and SEMA4A genes." (PMID 40756031, 2025). "To further elucidate the involvement of the SEMA4A/MAPK pathway in sepsis, we developed a THP-1 cell model with silenced SEMA4A expression." (PMID 40756031, 2025). "Additionally, correlation studies between core sepsis genes and immune cells unveil potential roles and regulatory effects of NTSR1, LRPAP1, and SEMA4A on immune cells in sepsis." (PMID 40756031, 2025). "Notably, the SEMA4A/MAPK signaling pathway is highlighted as pivotal in driving the initiation and progression of sepsis within monocytes." (PMID 40756031, 2025). "This study proposes SEMA4A, LRPAP1, and NTSR1 as promising therapeutic targets for sepsis." (PMID 40756031, 2025).
small cell lung carcinoma (1 paper, 2018). Small cell lung cancer (SCLC) is a highly aggressive malignant neoplasm, accounting for 10-15% of lung cancer cases, characterized byrapid growth, and early metastasis. "We have found a low to absent Sema4A expression in bronchioalveolar, papillary, and small cell lung cancer but stage-dependent increased levels of Sema4A in adenocarcinoma and squamous cell carcinoma." (PMID 30598022, 2018).
synovitis (1 paper, 2023). Inflammation of a synovial membrane. "The combination which provided the best predictive value was a DAS28 > 3.2 and/or presence of active synovitis on PDUS and/or SEMA4A concentrations > 94 ng/mL (HR 10.42, 95% CI 1.41–76.94 for treatment failure and 4.88, 95% CI 1.50–15.89 for flares)." (PMID 37669994, 2023). "The highest predictive value of treatment failure was obtained with the combination of increased circulating SEMA4A and/or Disease Activity Score (DAS) 28-CRP > 3.2 and/or active synovitis on doppler ultrasound (HR 10.42, 95% CI 1.41–76.94)." (PMID 37669994, 2023). "SEMA4A was complementary to the DAS28 > 3.2 and the presence of active synovitis on PDUS to predict treatment failure, given the high predictive value of these 3 variables alone or in combination." (PMID 37669994, 2023).
tumor (37 papers, 2013 to 2025). "In this mini-review, we discuss these findings as well as our data on Sema4A regulation of inflammation and angiogenesis, which both are important pathologic processes underlining tumorigenesis and tumor metastasis." (PMID 30598022, 2018). "Loss of the SEMA4A wild-type allele accompanied by amplification of the mutant one might be one mechanism of tumour suppressor inactivation in this particular entity." (PMID 25307848, 2014). "Finally, we were interested whether somatically acquired SEMA4A mutations are prevalent in sporadic CRCs as well as other neoplasms." (PMID 25307848, 2014). "Interactions of PLXNB2 with its ligands SEMA4C on tumor cells and SEMA4A on myeloid cells (monocytes) promote homotypic and heterotypic CTC cluster formation, respectively, thereby driving lung metastasis." (PMID 40818975, 2025). "Conversely, cancer zone B utilized Sema4a/d-Plxnb2 and Pros1-Axl interactions to coordinate crosstalk within cancer_macro 1 populations, driving immune evasion and promoting tumor invasion and metastasis." (PMID 40723284, 2025). "To further determine the association of SEMA4A with heterotypic tumor-monocyte clustering, we sorted SEMA4A+ and SEMA4A− THP1 cells and genetically knocked down SEMA4A in THP1 cells for co-culture with PB2 WT and KO TNBC cells." (PMID 40818975, 2025). "Within the TME, tumor-derived SEMA4A can activate cytotoxic T cells, contributing to anti-tumor immune responses." (PMID 40597436, 2025). "LILRB2 is known to inhibit immune cell activity and modulate the tumor immune microenvironment through its interaction with ligands such as HLA-G, angiopoietin-like protein 2, and semaphorin-4A, thereby promoting tumor cell proliferation and metastasis." (PMID 41383852, 2025). "Comparing T cell gene expression between treatments revealed a significant increase in Klrk1, Klrc2, Klrd1, Fasl, and Sema4a in CD4 T cells at the tumor site after HVJ-E/OX40 antibody injection." (PMID 39534532, 2024). "Adoptive transfer of HDVax-induced LILRB4+SEMA4a− or LILRB4+SEMA4a+ mItgb1-specific CD4+ T cells comparably ablated T3 tumour rejection in the Rag2−/− ACT assay." (PMID 39048822, 2024). "The majority tumor-infiltrating Tregs express Nrp1, which enhances their immunosuppressive role by interacting with Semaphorin 4A (Sema4A)." (PMID 38509593, 2024). "The majority of tumor-infiltrating Tregs express Nrp1, which interacts with its ligand, semaphorin 4A (Sema4A)." (PMID 39000453, 2024). "In AKPS liver metastases, SEMA4A+ tumour cells contact hepatocytes at the metastatic leading edge, and class IV semaphorins (Sema4a, Sema4c, Sema4d and Sema4g) are widely expressed." (PMID 39048831, 2024). "They showed that the tumor cell-derived Sema4A engagement of Plexin B1 on CD8+ T cells increased the effector function of CD8+ T cells and improved the anti-tumor efficacy of PD-1 blocking Ab." (PMID 38259471, 2023). "In this study, we have pinpointed SEMA4A as a novel modulator of tumor cell migration and metastasis both in vivo and in vitro." (PMID 37779872, 2023). "Concerning the cellular locations of SEMA4A, positive staining was confined mainly to the nucleus and cytoplasm compared to a negatively stained adjacent non-tumor tissue and BPH ones." (PMID 37779872, 2023). "The results further support that SEMA4A is a functional element in the tumor microenvironment to exacerbate disease progression." (PMID 37779872, 2023). "Sema4a is a Semaphorin that functions in angiogenesis, tumor and immune responses and plays an important role in T-cell activation and the balance between Th1 and Th2 cell responses." (PMID 36316644, 2022). "Within HD tonsil GC and non-tumor GC (GC within tumor-adjacent normal oropharyngeal tissue), SEMA4A and BCL6 co-localize as expected." (PMID 34099645, 2021).
tumor (continued). "Recently, semaphorin 4a (Sema4A) was described as a novel NRP1 ligand critically involved in suppression of anti-tumor responses by mTregs, but additional ligands mediating immune-modulatory effects of NRP1 are not well-defined." (PMID 31572401, 2019). "In contrast to Sema3A tumor suppressor effects, Sema3E, which shares Plexin D1 receptor with Sema4A and Sema4D, consistently demonstrated the pro-tumoral effects." (PMID 30598022, 2018). "Data from the cBioPortal for Cancer Genomics indicate that the SEMA4A gene is amplified in a wide range of different tumours and that deletions are only rarely seen." (PMID 25307848, 2014). "Recently, it has been shown that Sema4A expressed in plasmacytoid dendritic cells (pDCs) can modulate anti-tumor responses by potentiating regulatory T-cell function and stability in the tumor microenvironment." (PMID 24324469, 2013). "PLXNB2 is identified as a driver that promotes both homotypic and heterotypic CTC clustering through its interactions with Semaphorin ligands SEMA4C on tumor cells and SEMA4A on monocytes, in addition to PLXNB2 functions in proliferation and other known functions." (PMID 40818975, 2025). "Besides, tolerogenic tumor-associated DCs express IDO (indoleamine 2,3 dioxygenase), PD-L1, or semaphorin-4a (the ligand for Nrp1) to resist the inflammation-induced reprogramming of Tregs in vivo." (PMID 39227959, 2024). "All these support that SEMA4A may act as a tumor promoter in PCa and it could exacerbate the tumor phenotype and promote metastasis of PCa cells." (PMID 37779872, 2023). "Interestingly, loss of SEMA4A alone in monocytes was sufficient to reduce the size of heterotypic PLXNB2+ tumor clusters which is comparable with the effects of PB2 KO in tumor cells, suggesting that SEMA4A is the primary ligand on monocytes for PLXNB2-dependent tumor-monocyte clustering." (PMID 40818975, 2025). "The membrane-bound glycoprotein semaphorin-4A (SEMA4A), crucial for T cell co-stimulation and a key driver of Th 2 responses, plays an important role in generating immune aggregates through interactions between tumor-infiltrating B cells (TIL-Bs), endothelial cells, and T cells." (PMID 40486875, 2025). "In addition, SEMA4A could regulate the secretion of IL-10 in stromal cells and coordinates with IL-10 to promote tumor cell invasion via inducing Epithelial-mesenchymal transition." (PMID 37779872, 2023). "To determine the protein interactions between monocyte SEMA4A and tumor cell PLXNB2, we utilized the THP1 monocytic cells which express high SEMA4A ( > 80%) as an alternative source of human monocytes for heterotypic cluster formation." (PMID 40818975, 2025). "Using human tumor cell-THP1 clusters at an optimized 1:4 ratio and anti-PLXNB2 antibody for co-immunoprecipitation, we also detected the enrichment of SEMA4A and CDC42 in the PLXNB2 protein complex, compared to monocytes only." (PMID 40818975, 2025). "Sema4A on DC interacting with its Plexin B2 receptor on CTL can promote INF-γ production, increase the cytotoxicity of CTLs, and repress tumor growth." (PMID 35155237, 2022). "As Sema4A is downstream of VEGF-induced signaling in the lung tissues, its effects on angiogenesis and tumor progression were of significant research interest." (PMID 30598022, 2018). "Another potential therapeutic target in anti-angiogenic tumor management is Sema3G which also shares NRP-1 receptor with Sema3A and Sema4A." (PMID 30598022, 2018). "RCRC, on the other hand, is immunostimulatory, and enhancing immune signaling crosstalk, such as SEMA4A-PLXND1 between immune and tumor cells could be advantageous." (PMID 41450739, 2025). "By contrast, adoptively transferred SEMA4a single-positive cells or double-negative cells did not inhibit tumour rejection." (PMID 39048822, 2024).
tumor (continued). "IL-33, as a candidate for cytokine therapies, can effectively enhance Sema4A expression and stimulate anti-tumoral cells including NK and CD8+ T cells, while the mechanism of IL-33 on anti-tumor effects remains unclear." (PMID 35155237, 2022). "Sema4A–Nrp1 blockade via antibodies or soluble antagonists is possible to limit tumor growth by targeting Treg cells without triggering autoimmunity." (PMID 35155237, 2022). "This suggests SEMA4A could be important in both the development of GC B cells and the interactions between LZ GC B cells and TFH cells in normal and tumor tissues." (PMID 34099645, 2021). "The pro-angiogenic effect of Sema4A in the context of tumor is indirectly mediated by signaling through Plexin-D1-expressing macrophages, which induce VEGF-A expression and thereby enhance tumor vasculature." (PMID 32210960, 2020). "Certain target genes (e.g., ERBB4, SEMA4A, GCNT2 and SOX4) play critical roles in shaping two pathways related to the malignant fate of AT2 cells, which are inseparable from tumor differentiation and migration, suggesting that these genes may be novel therapeutic targets for further studies." (PMID 41415280, 2025). "As Sema4A regulates the immune response to different antigens such as allergens, infectious agents, and tissue-derived factors in autoimmunity, it is feasible to conclude that it plays a significant role in anti-tumor immunity that has not yet been assessed." (PMID 30598022, 2018). "Moreover, we report differential PBMC expression profiles that correlate inversely with disease stage (SEMA4A, SNAI1, PLXNA1 and VEGFR3) and can differentiate between the TNBC and non-TNBC tumor subtypes (VEGFR3 and PLXNA1)." (PMID 28607365, 2017). "SEMA4A+ monocytes with PLXNB2+ tumor cells (double positive) formed the largest clusters with more cell counts per cluster and in highest numbers of clusters compared to single-negative or double-negative combinations of SEMA4A−/+ monocytes with PLXNB2+/− tumor cells in heterotypic clustering." (PMID 40818975, 2025).
cancer (13 papers, 2014 to 2025). A tumor composed of atypical neoplastic, often pleomorphic cells that invade other tissues. "SEMA4A has been identified as a participant in various cancer processes, including the facilitation of epithelial-to-mesenchymal transition (EMT) in cancer cells and the contribution to drug resistance." (PMID 39062540, 2024). "Several genes relatedto oxidative stress including HMOX1, and the colorectal cancer-relatedgene SEMA4A were upregulated similarly between the enzymatic acroleinproduction system or pure acrolein." (PMID 39155646, 2024). "Few studies have investigated the mechanistic roles of LINC00886, SNUPN and SEMA4A in cancer initiation." (PMID 32139696, 2020). "Further studies are warranted to elucidate Sema4A-ILT-4 roles in different diseases including cancer." (PMID 30598022, 2018). "Sema3A, which shares NRP-1 receptor with Sema4A, was identified as a potential anti-cancer semaphorin with anti-angiogenic signaling." (PMID 30598022, 2018). "Given the many potential impacts of Sema4A on tumors, its detailed investigation will be beneficial for basic and clinical cancer research." (PMID 30598022, 2018). "Furthermore, SEMA4A has been extensively investigated in several pathological conditions, including cancer and immunological disorders." (PMID 39062540, 2024). "Finally, in dendritic cells and several cancer cell lines, Scrib was found to control cell migration downstream of the transmembrane semaphorin 4A (Sema4A)." (PMID 34673778, 2021). "Understanding the role of Sema4A in those processes may guide the development of improved therapeutic treatments for cancer." (PMID 30598022, 2018). "As the expression and function of sICAM-1 in cancer has been well characterized, which further supports the pro-migration ability of SEMA4A in the pathological progression of PCa, more attention is paid on the biological activity of IL-10, as well as its relation with SEMA4A." (PMID 37779872, 2023). "In cancer zone B, the SEMA4 pathway relied on Sema4a-Plxnb2, Sema4d-Cd72, and Sema4d-Plxnb2 interactions, with Sema4a/d-Plxnb2 showing particularly strong communication between cancer_macro 1 cells." (PMID 40723284, 2025). "Thus, considering the opposite effects of Sema4A on endothelial cells and macrophages, the identification of additional mechanisms of its action should be an important focus of future research aimed to develop of Sema4A-based therapeutic strategies to target cancer angiogenesis." (PMID 30598022, 2018). "We highlight cancer-specific down regulation of NRP-1, SNAI1 and SEMA4A in PBMCs with a further decrease of SNAI1, SEMA4A, VEGFR3 and PLXNA1 in patients with advanced disease." (PMID 28607365, 2017). "The function of Sema4A in angiogenesis and cancer is not defined." (PMID 30598022, 2018). "However, SEMA4A expression on GC TIL-B has not been previously reported in human cancer." (PMID 34099645, 2021). "Second, region-specific ligand–receptor interactions between cancer cells and CAFs—such as ANGPTL4–SDC2, PROS1–AXL, and SEMA4A/D–PLXNB2—have not been systematically validated in large clinical cohorts, and their therapeutic relevance in clinical contexts remains to be determined." (PMID 40723284, 2025).
infection (2 papers, 2019 to 2021). The state of being infected such as from the introduction of a foreign agent such as serum, vaccine, antigenic substance or organism. "The specific genes in the geneset that associated with the greatest odds of reduced risk of infection including SEMA4A, CTSD, CD68, and GAA were all members of this pathway, but not TNFSF13 (APRIL) which was the most protective gene in the NHP studies." (PMID 34533134, 2021). "In the acute infection with the nonpersistent FS73 strain, these interactions with semaphorin 4A-expressing antigen-presenting cells would be limited to lung-draining dendritic cells and infected lung epithelial cells but few B cells." (PMID 31118303, 2019).
inflammation (1 paper, 2015). Aberrant reaction of the microcirculation characterized by movement of fluid and leukocytes from the blood into extravascular tissues. "To study the association between Sema4A and chronic joint inflammation in RA, we first compared the expression profile of Sema4A mRNA in the synovial tissue of patients with RA and those with non-inflammatory OA." (PMID 26303122, 2015).
neurological diseases (1 paper, 2023). "SEMA4A encoded one class of semaphorin, which was often involved in immune responses and neurological diseases." (PMID 37842648, 2023).
retinal disorder (1 paper, 2014). Any disease or disorder of the retina. "A three-dimensional protein model of human SEMA4A predicts that Val78 has no spatial relationship to residues associated with retinal disorders." (PMID 25307848, 2014).